APOL1 (apolipoprotein L1)
Diseases named in the same sentence as APOL1 in open-access papers (continued):
Sharing a sentence is not in itself a finding about the gene and the disease.
preeclampsia (13 papers, 2016 to 2026). Preeclampsia is a hypertensive disorder of pregnancy that is characterized by new-onset hypertension with proteinuria presenting after 20 weeks of gestation, and depending on mild or severe forms may initially present with severe headache, visual disturbances, and hyperreflexia. "And fetal APOL1 variants, which are found almost exclusively in individuals of African ancestry, strongly link to preeclampsia and other adverse pregnancy outcomes, and forced placental expression of these APOL1 variants causes preeclampsia in mice." (PMID 41480768, 2026). "Cohort studies of African Americans, other African diasporas, and sub-Saharan African communities found fetal APOL1 high-risk genotype predisposes the mother to risk for preeclampsia and infants born with low birth weight." (PMID 40940784, 2025). "Several human cohort studies have now confirmed APOL1 high-risk genotypes in the infant predispose the mother to preeclampsia, resulting in infant prematurity and low birth weight." (PMID 40940784, 2025). "These were the same transgenic mouse models that also exhibited preeclampsia and low birth weights with APOL1 risk allele expression." (PMID 40940784, 2025). "Animal models of human APOL1 expression revealed the potential contribution of APOL1 risk variants to preeclampsia." (PMID 40940784, 2025). "Further investigation of this disease process is warranted to identify novel therapeutic targets for APOL1-associated preeclampsia." (PMID 39803524, 2024). "We established and characterized mouse models of APOL1-associated preeclampsia, in order to investigate the role of fetal APOL1 variants during pregnancy." (PMID 39803524, 2024). "Our study addresses an important disease in pregnancy with significant morbidity and mortality that has not been well studied in large populations in Africans with a high burden of preeclampsia and APOL1 high risk genotypes." (PMID 36580463, 2022). "The aim of the study is to understand the contribution of APOL1 risk variants to the development of preeclampsia in pregnant women in Ghana." (PMID 36580463, 2022). "APOL1 conferred a 2-fold increased risk of preeclampsia for fetuses carrying homozygotes or compound heterozygotes (G1/G1, G2/G2, or G1/G2), termed the high-risk genotypes." (PMID 36580463, 2022). "Determination of risk of both maternal and infant APOL1 risk variants and association with preeclampsia." (PMID 36580463, 2022). "In this regard, when expressed as transgenes in mice, both wild‐type APOL1 and the APOL1 variants triggered preeclampsia, but with less severity in case of the wild‐type." (PMID 32530132, 2021). "Either fetal or maternal expression of the APOL1 variants was significantly linked to maternal preeclampsia, likely through trophoblast dysfunction." (PMID 32530132, 2021). "Preeclampsia appears to be another disease associated with APOL1 variants, however, further studies are needed to increase confidence in the mode of inheritance." (PMID 32434471, 2020). "The infant APOL1 genotype was significantly associated with preeclampsia in a dominant inheritance pattern with odds ratio of 1.41 (P=0.029, 95% CI 1.037, 1.926)." (PMID 32434471, 2020). "Using logistic regression models, associations between fetal APOL1 genotype and preeclampsia were evaluated using several case definitions based on prematurity and severity of preeclampsia, with uncomplicated term pregnancies as controls." (PMID 32434471, 2020). "A recent genetic study identified ApoL1 risk alleles as being associated with incident preeclampsia [51•]." (PMID 31123841, 2019). "Vascular, immune/inflammatory and cellular homeostasis genes may be ideal starting points for future research, and further validation of the role of APOL1 G1 or G2 risk alleles in preeclampsia may be essential." (PMID 41898457, 2026).
preeclampsia (continued). "When excluding other psychosocial and economic confounders that can contribute to pregnancy complications, the fetal APOL1 high-risk genotype still accounts for a significant portion of the excess risk of preeclampsia in African ancestry compared to European ancestry." (PMID 40940784, 2025). "In speculation, a possible mechanism for APOL1-associated preeclampsia may be similar to the APOL1 risk variant cytotoxicity described for podocyte cell death in CKD." (PMID 40940784, 2025). "In addition to APOL1 kidney disease, APOL1 risk variants are also associated with preeclampsia and other conditions related to placental insufficiency." (PMID 40940784, 2025). "An early experimental attempt to develop a small animal model for human APOL1 expression serendipitously discovered that APOL1 risk alleles are also expressed in the placenta and cause preeclampsia, another disease with excess risk in mothers of African descent." (PMID 40940784, 2025). "Fetal APOL1 high-risk genotype increases preeclampsia risk, although mechanisms remain elusive." (PMID 39803524, 2024). "We report potential mechanisms of fetal APOL1 high-risk variant-induced preeclampsia." (PMID 39803524, 2024). "Fetal-maternal mismatch of APOL1 genotype has been reported to be a risk factor for preeclampsia." (PMID 39803524, 2024). "In patients, other factors may contribute to severe preeclampsia, in addition to fetal APOL1 high-risk genotype." (PMID 39803524, 2024). "It is also conceivable that APOL1 expression in the placenta may play a causal role in preeclampsia, which may be modulated by either maternal or infant APOL1 genotype." (PMID 36580463, 2022). "Recent studies have shown that APOL1 risk variants contribute to the risk of preeclampsia." (PMID 36580463, 2022). "The gene APOL1 has been implicated in preeclampsia, consequently, the role of APOL1 in populations of African origin may achieve opportunities for improved diagnosis and management." (PMID 36580463, 2022). "The association of preeclampsia with carriage of APOL1 risk alleles was evaluated in a case-control study of deliveries from black women at a single center in Cleveland, Ohio that included gross and histopathologic evaluations of placental tissues (395 cases and 282 controls)." (PMID 32434471, 2020). "By understanding the association of APOL1 variants with preeclampsia, genetic screening tests for APOL1 may be useful to predict at-risk pregnancies and targeted interventions may be developed to improve pregnancy outcomes." (PMID 32434471, 2020). "Besides the important mutation in APOL1, there seem to be a lot of other genetic factors, predisposing for the development of HIVAN in children, and recently APOL1 mutations were also discussed to induce preeclampsia in a transgenic mouse model." (PMID 27294131, 2016). "If APOL1 risk variant expression similarly results in trophoblast cell death, there may be too few trophoblasts to induce spiral artery remodeling, setting in motion the well-known mechanism for preeclampsia and placental insufficiency." (PMID 40940784, 2025). "In addition, high-risk APOL1 genotypes may present a higher proportion in infants born from birth complications by preeclampsia and may have poor perinatal outcomes." (PMID 36580463, 2022). "Recent studies suggest these APOL1 variants also may contribute risk for preeclampsia." (PMID 32434471, 2020). "The BAC/APOL1 IVF mouse model showed that fetal APOL1-G1 induced preeclampsia in dams, together with intrauterine fetal growth restriction of G1 fetuses." (PMID 39803524, 2024). "It is known that preeclampsia results in part from microangiopathy in the glomerulus of the kidney suggesting a potentially important role of APOL1 in preeclampsia." (PMID 36580463, 2022). "Placentas of Tg mice expressed APOL1, similar to human placenta, suggesting a role for APOL1 in preeclampsia." (PMID 36580463, 2022).
preeclampsia (continued). "The overarching objective for the APOL1 characterization in preeclampsia is to undertake a comprehensive genotype-phenotype of a cohort with translational potential." (PMID 36580463, 2022). "The overall aim is to understand the influence of APOL1 on preeclampsia and its sequelae on both perinatal and maternal outcomes using a case- control design." (PMID 36580463, 2022). "The risk for preeclampsia, prematurity, or low birth weight was specific to the fetal APOL1 genotype and did not associate with the maternal APOL1 genotype." (PMID 40940784, 2025). "An interesting caveat of these observations was that the risk of preeclampsia was dependent on the APOL1 genotype of the fetus not the mother, implicating an important contribution of the paternal APOL1 genotype to preeclampsia risk." (PMID 40940784, 2025). "We characterized two mouse models to investigate whether fetal-origin APOL1 induces preeclampsia and which cell types contribute." (PMID 39803524, 2024). "This removes from our study population women who might have recurrent preeclampsia due to their (or their fetus’) APOL1 status." (PMID 36580463, 2022). "This may result in an underestimate of the relationship between APOL1 and preeclampsia." (PMID 36580463, 2022). "Moreover, those women who developed preeclampsia in association with the fetal risk allele had an increased prevalence of cerebral symptoms as compared to women with preeclampsia without the associated fetal ApoL1 risk allele." (PMID 31123841, 2019). "The existing literature on the relationship between these proteins and preeclampsia is limited, underscoring the importance of further research to elucidate the role of APOC1 and APOL1 in the pathophysiology of preeclampsia and their potential use as biomarkers or therapeutic targets." (PMID 39201423, 2024).
acute kidney injury (10 papers, 2013 to 2025). Sudden and sustained deterioration of the kidney function characterized by decreased glomerular filtration rate, increased serum creatinine or oliguria. "In that study, high-risk APOL1 genotypes were more strongly associated with acute kidney injury than the need for mechanical ventilation or vasopressors." (PMID 37882666, 2023). "In African Americans infected with SARS-CoV-2, carriage of two APOL1 variants is associated with collapsing glomerulopathy, acute kidney injury, persistent AKI, and requirement for kidney replacement therapy." (PMID 38360481, 2024). "Recently, in SARS-CoV-2-infected African Americans, carriage of two high-risk APOL1 variants has been associated with collapsing glomerulopathy, acute kidney injury (AKI), persistent AKI, and requirement for kidney replacement therapy." (PMID 38360481, 2024). "Zhao and colleagues found that rs62341639 and rs62341657 polymorphism on chromosome 4 near the APOL1 regulator IRF2 and rs9617814 and rs10854554 polymorphism on chromosome 22 close to the acute kidney injury-related gene TBX1 were associated with AKI development but without genome-wide significance." (PMID 34300206, 2021).
atherosclerosis (10 papers, 2017 to 2025). A disease characterized by the build-up of fatty material and calcium deposition in the arterial wall resulting in partial or complete occlusion of the arterial lumen. "With regard to atherosclerosis also, All of Us data for atherosclerotic disease supported the APOL1 mouse model observation." (PMID 39803526, 2024). "Transgenic mice carrying APOL1 (G0 and G1 variants) on bacterial artificial chromosomes (BAC/APOL1 mice) were crossed with the ApoE knock-out (ApoE-KO) atherosclerosis mouse model." (PMID 39803526, 2024). "An upregulated miR-193a-5p in EVs and plaques implies a reduced APOL1, which ultimately promotes atherosclerosis." (PMID 38725837, 2024). "Since liver is the major organ to produce ApoL1, we constructed a liver-specific adeno-associate virus 8 (AAV8) vector expressing ApoL1 G0 or ApoL1 G2 with AAV8-Null as a negative control to investigate the relationship between ApoL1 and atherosclerosis." (PMID 39669548, 2025). "Transgenic mice carrying APOL1 (G0 and G1 variants) on bacterial artificial chromosomes (BAC/APOL1 mice) were crossed with the apolipoprotein-E knock-out (ApoE-KO) dyslipidemia and atherosclerosis mouse model." (PMID 40459058, 2025). "As there was substantial atherosclerosis and calcification in all APOL1-transgenic mice at nine months of age, differences among groups might have been present at time points that were not studied." (PMID 40459058, 2025). "As there was substantial atherosclerosis and calcification in all APOL1-transgenic mice at 9-months of age, differences among groups might have been present at time points that were not studied." (PMID 39803526, 2024). "As for the similarities in the EV profile of IS and MI patients, we found that APOL1 and APOC1-derived EVs might be related to risk factors such as atherosclerosis." (PMID 33374290, 2020). "Importantly, our findings on platform-dependent pQTL effects of the APOL1 V1 mutation and KKS variants are independently corroborated by recent data from the Multi-Ethnic Study of Atherosclerosis (MESA), which collected Olink and SomaLogic measurements for ~2,000 plasma proteins." (PMID 39975113, 2025). "Since apoptosis of endothelial cells is a crucial event in atherosclerosis and CVD, this suggests that apoL-1 could be involved in atherogenesis." (PMID 30842338, 2019). "Different transgenic murine models expressing human ApoL1 risk alleles have been constructed; however, they are widely used to investigate the impact of ApoL1 on kidney diseases but not atherosclerosis because wild-type mice with overnutrient intervention are still resistant to atherosclerosis." (PMID 39669548, 2025).
malaria (10 papers, 2013 to 2025). Malaria is a serious and sometimes fatal disease caused by a parasite that commonly infects a certain type of mosquito which feeds on humans. "We lack comprehensive data from Western Africa, a region characterized by seasonal malaria transmission, where a relatively high incidence of kidney risk variants (e.g., APOL1), which may influence susceptibility to AKI and affect kidney recovery." (PMID 41333437, 2025). "Infectious diseases such as malaria, cholera, dengue, and typhoid have affected millions of people in sub-Saharan Africa for centuries and may have driven the selection of APOL1 variants but are either rare or absent from the cohort described here." (PMID 38360481, 2024). "Notably, complement genes (C1QA, C1QB, C1QC), apoptotic genes (PDL1, PDL2, APOL1, APOL2, FAS), inflammatory caspases (CASP1, CASP5), TLR pathway genes (TLR1, TLR4, TLR5, TLR8), cytokines (IL6, IL10), and granzyme (GZMB) were among the genes upregulated during symptomatic malaria." (PMID 39161730, 2024).
systemic lupus erythematosus (10 papers, 2011 to 2025). An autoimmune multi-organ disease typically associated with vasculopathy and autoantibody production. "A strong association has been extensively shown between collapse and homozygous APOL1 gene risk variants (G1 and G2) in patients with HIV and parvovirus B19, systemic lupus erythematosus (SLE), and some drugs such as pamidronate and interferon." (PMID 39792859, 2025). "Various factors such as heredity including APOL1 gene variations, infection, hypertension, inflammatory diseases such as systemic lupus erythematosus (SLE) and inflammatory bowel disease, drug-related side effects, and unknown causes have been involved in the pathogenesis of the disease." (PMID 34795786, 2021). "APOL1 has now been demonstrated to be related to HIVAN and FSGS, to collapsing nephropathy in lupus patients and to the younger age of initiation of dialysis." (PMID 24658608, 2014). "For instance, Apolipoprotein L1 (APOL1) variant alleles, and not corticosteroids, were associated with AVN among African American patients with lupus." (PMID 33739994, 2021).
nephrotic syndrome (9 papers, 2013 to 2025). A collection of symptoms that include severe edema, proteinuria, and hypoalbuminemia; it is indicative of renal dysfunction. "The presence of APOL1 is known to directly cause CG, nephrotic syndrome, AKI, and ESRD35–50." (PMID 36845824, 2023). "Using this approach, we found novel or known COL4A3 or COL4A5 mutations in a subset of patients with clinically diagnosed or suspected AS, APOL1 variants associated with FSGS in African Americans and novel mutations in genes associated with nephrotic syndrome." (PMID 24130771, 2013). "This is probably the first reported case of FAN 1 mutation causing nephrotic syndrome and CKD in a patient of African ancestry, raising the possibility of other novel mutations besides the apolipoprotein L1 gene mutation (APOL 1) in CKD pathogenesis among African diaspora." (PMID 39114219, 2024). "FAN 1 mutation presenting as nephrotic syndrome with CKD is a rare clinical entity and this differential diagnosis has to be considered while evaluating patients of African lineage besides the conventional APOL1 mutation." (PMID 39114219, 2024). "To deduce how the M1-G2 haplotype formed, we examined APOL1 haplotypes in individuals of AFR ancestry from the 1000 Genomes Project, the Nephrotic Syndrome Study Network (NEPTUNE) cohort, and an ancient individual from Africa." (PMID 39658338, 2025). "Here, we examined APOL1 haplotypes in individuals of AFR ancestry from the 1000 Genomes Project, the Nephrotic Syndrome Study Network (NEPTUNE), and an ancient individual from the Allen Ancient Genome Diversity Project to determine how the M1-G2 haplotype arose." (PMID 39658338, 2025).